BRCA1 (BRCA1 DNA repair associated)
Diseases named in the same sentence as BRCA1 in open-access papers (continued):
Sharing a sentence is not in itself a finding about the gene and the disease.
Lynch syndrome (184 papers, 2008 to 2026). An autosomal dominant hereditary neoplastic syndrome characterized by the development of colorectal carcinoma and a high risk of developing endometrial carcinoma, gastric carcinoma, ovarian carcinoma, renal pelvis carcinoma, and small intestinal carcinoma. "Beyond the well-established BRCA1/2 and Lynch syndrome genes, large panels can identify pathogenic variants in other moderate-to-high penetrance genes, such as PALB2 and CHEK2, which are implicated in both breast and colorectal cancer risks." (PMID 41378290, 2025). "Testing is increasingly performed to identify clinically relevant germline and/or somatic variants in BRCA1/2 in four cancer entities and to detect microsatellite instable tumors, possibly related to Lynch syndrome, which requires further workup." (PMID 41210226, 2025). "In contrast, clinical genetic testing for specific diseases (which in 2020 only included “High risk cancer testing for example, BRCA1/2 or Lynch Syndrome”) has increased from 36% to 55% and use has increased from 5% to 16%." (PMID 39582788, 2024). "Even though most OC with germline mutation are due to alterations in BRCA1/2, some are also associated with Lynch syndrome." (PMID 39562613, 2024). "Hysterectomy should be considered in women with an increased risk of endometrial cancer, BRCA1 mutations, Lynch syndrome or exposure to tamoxifen." (PMID 39274288, 2024). "Testing premenopausal patients diagnosed with epithelial OC for both BRCA1/2 and Lynch syndrome is justified, as the cumulative risk of OC in these conditions is similar." (PMID 39768893, 2024). "Only a limited number of studies included women with a hereditary high‐risk profile (i.e., BRCA1/2 pathogenic variant carriers, Lynch syndrome patients and/or PHTS patients)." (PMID 39031958, 2024). "As a preventive application, an IPSC-based vaccine can be used to treat high-risk populations with Lynch syndrome or pathogenic germline mutations of the BRCA1/2 gene." (PMID 38058983, 2023). "In our patient population meeting genetic test criteria for HBOC or Lynch syndrome, 12.5% of patients were found to have a pathogenic mutation, with the most common being in BRCA1/2 followed by MUTYH and CHEK2." (PMID 38136308, 2023). "BRCA1/2 mutations are associated with the majority of hereditary ovarian cancer or Lynch syndrome and the mutation rate of BRCA1/2 increases in recurrent HGSOC." (PMID 35954453, 2022). "Among patients who met testing criteria for only BRCA1/2 or only Lynch syndrome and presented positive pathogenic variants (PV), mutations were present in the respective genes in 33.1 and 46.2 %." (PMID 34289891, 2021). "When an individual is found to have a germline BRCA1/BRCA2 mutation in HBOC or a DNA mis-match repair gene mutation in Lynch syndrome, the individual should inform their at-risk family members about the option of presymptomatic DNA testing." (PMID 34525964, 2021). "Future large-scale studies are needed in general population or in people who have a genetic disposition to acquire certain types of cancer (e.g., patients with mutation in BRCA1/2 or Lynch syndrome)." (PMID 33634328, 2021). "Clinical testing (n = 304) was performed using the Ashkenazi 3-site mutation panel (n = 5), BRCA1/2 sequencing (n = 142), Lynch syndrome testing (n = 1), and multi-gene panel testing (n = 156)." (PMID 31963545, 2020).
Lynch syndrome (continued). "Four out of eleven tumors revealed a BRCA mutation (two cases with BRCA1 mutations, one case with a BRCA2 mutation and an additional case with known Lynch-syndrome showing co-occurrence of BRCA1 and BRCA2 mutations)." (PMID 30717682, 2019). "Population carrier rates for these pathogenic variants are high, ranging from 1/40 to 1/400 for BRCA1/2 (depending on ethnic background) and 1/300 to 1/400 for Lynch syndrome." (PMID 30734520, 2019). "The tumor of a fourth patient with known Lynch-syndrome revealed a BRCA1 as well as a BRCA2 mutation both classified as class 3 mutations and therefore probably not therapeutically important." (PMID 30717682, 2019). "This is particularly important for the gynaecological oncologist, as ovarian and endometrial cancers are the sentinel cancer for many women with either a BRCA1 or 2 mutations or Lynch Syndrome, and can be facilitated by a family history questionnaire." (PMID 29344385, 2018). "In genetic counseling for individuals at 50 % risk of carrying an inherited BRCA1/2 mutation or Lynch syndrome more focus should be placed on cancer worries besides general distress." (PMID 26475052, 2016). "Eight men were initially recruited but dropped out of the study, leaving 51 informative cases for analysis: 47 men linked to a family history of BRCA1/2 mutation and 4 men with family history of Lynch Syndrome." (PMID 27456091, 2016). "Counselees with a 50 % risk of BRCA1/2 or Lynch syndrome completed questionnaires at three time-points: after receiving a written invitation for a genetic counseling intake (T1), 2–3 days after receiving their DNA test result (T2), and 4–6 weeks later (T3)." (PMID 26475052, 2016). "The mean age and serum PSA levels were comparable between men from BRCA1/2 and Lynch Syndrome mutations." (PMID 27456091, 2016). "Contrary to serous sporadic OC and BRCA1-related OC, decreased susceptibility to cisplatin therapy has been suggested to be characteristic feature for Lynch syndrome-associated OC." (PMID 25606063, 2015). "Individuals with BRCA1/2 or Lynch syndrome gene mutations have improved outcomes after diagnosis with intensive cancer surveillance." (PMID 21311097, 2010). "This could explain a possible synergistic effect driving carcinogenesis, hence it imperative that BRCA/Lynch carriers are managed and screened for the whole spectrum of cancers associated with BRCA1/2 and Lynch Syndrome." (PMID 39843919, 2025). "Other studies concluded that high-risk women with a genetic predisposition (BRCA1/2, Lynch syndrome) may benefit from oophorectomy, while low-risk patients should consider ovarian preservation." (PMID 40278337, 2025). "Interestingly, PGT-M is less commonly used for genes associated with Lynch syndrome compared to the breast cancer susceptibility genes BRCA1/2, even though both conditions have similar prevalence and severity." (PMID 39768893, 2024). "Germline variants in the ATM gene were found more consistently across multiple primary tumor types and demonstrated a more consistent fraction of the overall germline variant burden than hereditary breast cancer (BRCA1/2) or Lynch syndrome genes in different tumors." (PMID 36261688, 2023). "Also, 78% and 62% of respondents were aware of the association between hereditary PC and BRCA2 mutations (BRCA2m) and BRCA1 mutations, respectively, but < 40% were aware of the association between hereditary PC and Lynch syndrome." (PMID 35924163, 2022). "In this analysis of population-representative data on sharing clinical genetic test results, 90% of those who underwent high-risk cancer genetic testing (e.g., BRCA1/2 and Lynch syndrome) shared results with HCP/GCs, whereas only 68% shared results with their FDRs." (PMID 36675679, 2022).
Lynch syndrome (continued). "Opportunities to improve upon identification of patients at risk for hereditary cancer predisposition include revising BRCA1/2 and Lynch syndrome testing criteria to include additional clinically actionable genes with overlapping phenotypes and relaxing testing criteria for associated cancers." (PMID 31406321, 2020). "ATM and BRCA1 were unexpectedly associated with moderately increased risk for colorectal cancer in this study, with 20.7% and 19.4% of PV carriers in these genes meeting testing criteria for Lynch syndrome." (PMID 31406321, 2020). "Opportunities to improve identification of patients at risk include revising BRCA1/2 and Lynch syndrome testing criteria to include a broader range of medically actionable cancer predisposition genes and relaxing criteria, such as age at diagnosis constraints, for patients with associated cancers." (PMID 31406321, 2020). "Gynaecological cancers may be the sentinel malignancy in women who carry a mutation in BRCA1 or 2, a mis-match repair gene causing Lynch Syndrome or other genes." (PMID 29344385, 2018). "Positive results were split relatively evenly between well-established genes—including BRCA1/2, Lynch syndrome, and other high-risk genes (51.8%)—and more recently described genes with moderate or unknown risk (48.2%)." (PMID 26681312, 2016). "Our study supports the notion that men with a family history of BRCA1/2 or Lynch Syndrome mutations may benefit from testing for PC, highlighting the role of MMR in prostate carcinogenesis." (PMID 27456091, 2016). "Importantly, this study did not assess genetic predisposition, such as germline mutations associated with Lynch syndrome or BRCA1/2, which may play a central role in cases involving multiple primary malignancies." (PMID 41155736, 2025). "The most common recommendations for targeted therapies are PARP inhibitors and immune checkpoint inhibitors, based on PGVs in homologous directed repairs, especially BRCA1 and BRCA2, and Lynch syndrome-associated genes, respectively." (PMID 41210226, 2025). "For women carrying mutations in high-risk genes such as BRCA1, BRCA2, or mismatch repair genes associated with Lynch syndrome, risk-reducing salpingo-oophorectomy (RRSO) and hysterectomy are established strategies endorsed by major guidelines." (PMID 40565763, 2025). "Of the 1474 patients who underwent genetic testing, PVs were identified in 123 individuals, including 76 actionable PVs (5.2%), of which 17 were in BRCA1 or BRCA2 and 11 were in Lynch syndrome–associated genes (eTable 4 in Supplement 2)." (PMID 40053353, 2025). "For example, in a recent multigene panel analysis, nearly one-third of patients with multiple primary tumors carried pathogenic germline variants, most commonly in BRCA1/2 and mismatch repair (MMR) genes associated with Lynch syndrome." (PMID 41155736, 2025). "Bilateral salpingo-oophorectomy (BSO) is the standard risk-reducing intervention recommended for individuals carrying germline mutations in the BRCA1 or BRCA2 genes, as well as for those with other high-risk gene mutations or a diagnosis of Lynch syndrome." (PMID 41463165, 2025). "Premenopausal BRCA1/2-pV carriers and carriers of pV in Lynch Syndrome genes should be offered hormone replacement therapy (HRT) after RRSO, to prevent diseases caused by estrogen deficiency." (PMID 39259360, 2024). "Other digital risk assessment tools, and also validation of those tools, have primarily focused only on BRCA1/2 and Lynch syndrome." (PMID 39516903, 2024).
Lynch syndrome (continued). "As expected, we found higher uptake in males for Lynch syndrome than for BRCA1/2 with a higher proportion of pre-symptomatic tests in males at 42% of all tests in males for Lynch compared to 25.8% for BRCA1/2 (P < 0.0001)." (PMID 38478259, 2024). "Individuals with cancer susceptibility syndromes such as BRCA1, BRCA2, and Lynch syndrome mutations face a greater lifetime risk of developing endometrial, ovarian, fallopian tube, and peritoneal cancers." (PMID 38698439, 2024). "Prophylactic oophorectomy and salpingectomy are recommended in Lynch syndrome (strength of evidence IIIB and IIIB) and in the case of detection of the germinal mutation BRCA1/2 (HOC/HBOC/HOC) (strength of evidence IIIA) (grade of recommendation 2A)." (PMID 36836017, 2023). "Patients with P/LP variants in BRCA1, BRCA2, or Lynch syndrome carriers face lifetime cancer risks of 20%–80%, including breast, ovarian, colon, and endometrial cancer." (PMID 38163482, 2023). "Gene-related cancer predisposition syndromes accounted for 16.7% (4/24) of ACMG SFs: MSH6 Lynch syndrome—1, BRCA1 hereditary breast and ovarian cancer (HBOC)—1, and PALB2 hereditary breast cancer (HBC)—2." (PMID 36635046, 2023). "The most frequent clinically diagnosed syndromes in probands were HBOC with 41 cases (BRCA1 in most cases), followed by eight cases of Lynch syndrome with MLH1 as the primarily responsible gene, and seven cases of breast cancer predisposition syndrome." (PMID 36833268, 2023). "In the summer of 2022, Palmetto/MolDX published a local coverage determination (LCD) addressing hereditary cancer panel testing broadly, replacing LCDs for BRCA1/2 and Lynch syndrome." (PMID 37435610, 2023). "Although tools have been developed for all three Tier 1 conditions, there are a larger number of tools, at more advanced stages of development and implementation for BRCA1/2 testing, compared to FH and Lynch syndrome." (PMID 36353115, 2022). "Several studies show that safety-net hospitals have successfully provided BRCA1/2 testing and Lynch syndrome screening and testing to low-income patients of diverse backgrounds." (PMID 35742117, 2022). "A 2015 study used population-level data to understand BRCA1/2 and Lynch syndrome genetic test result-sharing behavior and found high result-sharing with healthcare professionals and family members." (PMID 36675679, 2022). "State programs increasingly cover BRCA1/2 and Lynch syndrome genetic testing, though testing remains underutilized in racial and ethnic groups." (PMID 35742117, 2022). "Hereditary breast and ovarian cancer syndrome is frequently associated with germline mutations in the BRCA1 and BRCA2 genes, whilst Lynch syndrome is categorised by germline mutations in DNA mismatch repair genes." (PMID 33673083, 2021). "In an assessment of patients tested for all 32 cancer predisposition genes (n = 33,987), less than half of PVs in patients meeting criteria for only BRCA1/2 or only Lynch syndrome occurred in the respective genes (33.1% and 46.2%, respectively)." (PMID 31406321, 2020).
Lynch syndrome (continued). "Mutations in BRCA1/2, RAD51C/D, and Lynch syndrome genes were associated with a high OC risk, while mutations in BRIP1 were associated with a moderate OC risk in our study, in concordance with previous reports." (PMID 32295079, 2020). "Half of the detected pathogenic/likely pathogenic variants were found in BRCA1 (23%), BRCA2 (23%), or the Lynch syndrome-associated genes PMS2 (4%) and MLH1 (2%)." (PMID 32090079, 2020). "In this study, 67% of PVs in patients meeting criteria for only BRCA1/2 occurred in genes other than BRCA1/2, including 5.2% in Lynch syndrome genes." (PMID 31406321, 2020). "Fewer than half of PVs identified in patients meeting testing criteria for only BRCA1/2 or only Lynch syndrome occurred in the respective genes (33.1% and 46.2%)." (PMID 31406321, 2020). "A vast majority of patients (89.8%) met NCCN testing criteria for BRCA1/2 (83.9%) and/or Lynch syndrome (20.3%)." (PMID 31406321, 2020). "High-risk groups are patients with a positive family history of PC, hereditary PC, familial atypical multiple mole melanoma (p16 mutation), cystic fibrosis, Peutz–Jeghers syndrome, Lynch syndrome and HBOC (BRCA1/BRCA2 mutation)." (PMID 31717773, 2019). "For ovarian cancer, the Consensus Group strongly recommends somatic NGS on formalin-fixed paraffin-embedded or fresh frozen tumor tissue of nonmucinous invasive epithelial tumors, which should include BRCA1/2 and Lynch syndrome genes (grade B/C)." (PMID 30918358, 2019). "Direct access to genetic services was reported in 48 programs, predominantly for BRCA1/2, Lynch syndrome, and newborn screening." (PMID 31275354, 2019). "The main genetic tests offered under Model I are BRCA1/2 (43 programs), Lynch syndrome (16 programs) and newborn screening panel (9 programs)." (PMID 31275354, 2019). "Programs where pre- and post-test counseling were performed mostly comprised those offering testing for BRCA1/2 (52/59 programs) and Lynch syndrome (19/23 programs)." (PMID 31275354, 2019). "Leading examples of genetic tests with such specifications, and included in Tier 1, are BRCA1/2 genetic testing, genetic screening for Lynch syndrome, and FH." (PMID 31275354, 2019). "Cascade testing on relatives of index cases (probands) was performed in several genetic programs, mainly for BRCA1/2 Lynch syndrome; FH testing and newborn screening." (PMID 31275354, 2019). "The main genetic tests offered under Model III are BRCA1/2 (15 programs), Lynch syndrome (10 programs) and FH (eight programs)." (PMID 31275354, 2019). "Select syndromes are relatively prevalent genetic conditions, with mutations in the BRCA1 and BRCA2 genes and Lynch syndrome-related genes occurring in approximately 1 in 500 and 1 in 370 individuals, respectively." (PMID 30651894, 2019). "The main genetic tests offered under Model II are BRCA1/2 (14 programs), Lynch syndrome, FH, and diabetes (four programs each)." (PMID 31275354, 2019). "Regarding geographical distribution, BRCA1/2 testing was mostly provided in the UK (29; 49%) and the USA (11; 19%), Lynch syndrome testing in the UK (6; 26%), and the newborn screening panel in the USA (9; 50%)." (PMID 31275354, 2019). "Genetic tests, most commonly BRCA1/2 (59, 40%), Lynch syndrome (23; 16%), and the newborn screening panel (18; 12%), were offered in 145/148 genetic programs." (PMID 31275354, 2019). "The genetic tests offered were mainly for BRCA1/2 (59, 40%), Lynch syndrome (23, 16%), and newborn screening (18, 12%)." (PMID 31275354, 2019). "Seventy-six patients—31% of all pathogenic variant carriers—had a germline mutation in BRCA1 and/or BRCA2, and 39 (16%) had a pathogenic variant in a mismatch repair gene conferring a diagnosis of Lynch syndrome." (PMID 34322651, 2019). "Conversely, by testing families suspected to have Lynch Syndrome for 112 known or candidate colorectal cancer genes, Hansen and colleagues identified one BRCA1 carrier and two BRCA2 carriers." (PMID 28637432, 2017).